CCL3L3 (C-C motif chemokine ligand 3 like 3)
Description:
Chemotactic for lymphocytes and monocytes. Is a ligand for CCR1, CCR3 and CCR5. Is an inhibitor of HIV-1-infection. The processed form LD78-beta(3-70) shows a 20-fold to 30-fold higher chemotactic activity and is a very potent inhibitor of HIV-1-infection. LD78-beta(3-70) is also a ligand for CCR1, CCR3 and CCR5.
Synonyms: D17S1718; G0S19-2; SCYA3L1; MGC12815; 464.2; LD78; LD78BETA; SCYA3L
Tractability: Antibody: its Gene Ontology location is reachable by antibodies, with high confidence; UniProt places it where antibodies can reach, with medium confidence; UniProt predicts a signal peptide or a membrane-spanning region.
Gene: Protein-coding gene on chromosome 17 (36,194,869 to 36,196,758, reverse strand). Ensembl gene ENSG00000276085.
Subcellular location: Secreted
Pathways (Reactome):
Immune System: Interleukin-10 signaling
Signal Transduction: Chemokine receptors bind chemokines
Gene Ontology:
Molecular function: protein binding; CCR chemokine receptor binding; chemokine activity
Biological process: antimicrobial humoral immune response mediated by antimicrobial peptide; cell chemotaxis; chemokine-mediated signaling pathway; inflammatory response; negative regulation of cell population proliferation; positive regulation of cell migration; immune response
Cellular component: extracellular region
Genetic constraint (gnomAD): Loss-of-function variants: 7 observed, 8.17 expected, observed/expected ratio (o/e) 0.86, 90% interval 0.49 to 1.58. That is too few expected variants to judge how well the gene tolerates losing a copy. Missense variants: 93 observed, 105.77 expected, observed/expected ratio (o/e) 0.88, 90% interval 0.74 to 1.04. Synonymous variants: 38 observed, 37.82 expected, observed/expected ratio (o/e) 1, 90% interval 0.77 to 1.32.
Homologues: Orthologues: chimpanzee CCL3L3 (91% identical), macaque CCL3 (88% identical), pig CCL3L1 (76% identical), rat Ccl3 (76% identical), mouse Ccl3 (75% identical), dog CCL3 (71% identical), zebrafish ccl35.1 (34% identical), zebrafish ccl35.2 (34% identical). Paralogues in human: CCL3 (95% identical), CCL18 (59% identical), CCL4 (58% identical), CCL4L2 (55% identical), CCL23 (48% identical), CCL5 (48% identical), CCL15 (46% identical), CCL14 (44% identical), CCL13 (40% identical), CCL8 (40% identical), CCL11 (38% identical), CCL16 (38% identical), and 14 more.
Diseases named in the same sentence as CCL3L3 in open-access papers:
CCL3L3 is named in the same sentence as 67 diseases in open-access papers, as found by Europe PMC text mining. Sharing a sentence is not in itself a finding about the gene and the disease. The quoted sentences say what the papers report.
systemic lupus erythematosus (10 papers, 2010 to 2024). An autoimmune multi-organ disease typically associated with vasculopathy and autoantibody production. "CCL3L3 has been suggested to be involved in susceptibility to systemic lupus erythematosus, an autoimmune disease." (PMID 38416332, 2024).
melanoma (2 papers, 2021 to 2022). A malignant, usually aggressive tumor composed of atypical, neoplastic melanocytes. "Additionally, our study identified genes without reported expression in CMM and nevi or biological function related to melanoma progression, including CCL3L3, NPY1R, IL11A, FCGR1B, OAS2, ASB11, FCGR3A, and GLA." (PMID 35008167, 2021).
alopecia (1 paper, 2021). Hair loss usually from the scalp. "In the analysis of associations between CCL3L3-null status and clinical variables, CCL3L3-null status showed a significant association with non-scarring alopecia (P = 0.0434), whereas CCL3L1-null status did not (P = 0.2048)." (PMID 34580371, 2021). "The present study’s significant association of CCL3L3-null status but not of CCL3L1-null status with non-scarring alopecia may also suggest their differential roles." (PMID 34580371, 2021).
cholangiocarcinoma (1 paper, 2020). A carcinoma that arises from the intrahepatic biliary tree (intrahepatic cholangiocarcinoma) or from the junction, or adjacent to the junction, of the right and left hepatic ducts (hilar cholangiocarcinoma). "In contrast, mononuclear phagocytes exhibited up‐regulation of chemokines such as CCL4, CCL4L2, and CCL3L3 in the cholangiocarcinoma samples and extracellular remodeling genes such as MMP19, MMP12, and HS3ST2 in the metastatic patients." (PMID 33332768, 2020).
Salmonella Infections (1 paper, 2018). Infections with bacteria of the genus SALMONELLA. "On the other hand, FOXO signaling (TNFSF10, PRKAB1, GADD45B, STK4, STAT3), Salmonella infection (ARPC2, ARPC5L, CCL3L3, CCL4) and lysosome (LAPTM4B, HGSNAT, CD164, ATP6V0A2) pathways were up-regulated, albeit weakly, in the HLA-DR- Teff subset." (PMID 30231065, 2018).
tumor (25 papers, 2014 to 2026). "In treatment-naive samples, Mono_EREG exhibited high expression of CCL family genes (CCL3L3, CCL20), EREG, and BCL2A1, which are associated with tumor progression, suggesting functional impairment." (PMID 40725006, 2025). "Finally, in the CCL network, CCL3 and CCL3L3 produced by MG1, MG2, tumor-cell clusters 4 and 6, oligodendrocytes, and MDM5 engaged CCR1 on MG3, while CCL5—expressed exclusively by MDM5—also targeted MG3." (PMID 41503214, 2026). "SL exposure also induced changes in the expression of genes involved in metabolic functions in tumor and stem cells (ALDH1B1, ABCB1, SLC3A2, SLC44A2, SLC31A2, SLC7A11, CYP24A1, PTGS2/COX2, PPRC1), cytokines (CCL3L3, GDF15) and growth and differentiation factors (PGF, TGFBR11 and FOXD1)." (PMID 24742967, 2014).
infection (16 papers, 2008 to 2025). The state of being infected such as from the introduction of a foreign agent such as serum, vaccine, antigenic substance or organism. "Of these, four, C-C Motif Chemokine Ligand, CCL3L3; mitochondrial Glutathione-S-Transferase, GSTM1, F8A3 and F8A2, are directly related to the interrelated processes of infection, inflammation, endosomal motility, and ROS metabolism." (PMID 33972602, 2021).
cancer (11 papers, 2020 to 2025). A tumor composed of atypical neoplastic, often pleomorphic cells that invade other tissues. "CCL3L3 is also considered a proinflammatory M1 in the cancer microenvironment." (PMID 35795203, 2022).
CCL3L3 also shares sentences with these, for which no sentence is quoted: AIDS (17 papers); COVID-19 (10); HIV-1 infection (7); rheumatoid arthritis (7); autoimmune disease (5); Crohn disease (4); asthma (3); breast carcinoma (3); glioblastoma (3); psoriasis (3); type 1 diabetes (3); viral infection (3); atherosclerosis (2); co-infection (2); gastric cancer (2); Kawasaki disease (2); malaria (2); tuberculosis (2); adenomyosis (1); airway allergy (1); Allergy (1); anaemia (1); arteriosclerosis (1); atopic dermatitis (1); Autoimmunity (1); biliary tract cancer (1); central nervous system disorder (1); cerebral malaria (1); colorectal cancer (1); coronary artery diseases (1).
A further 29 diseases each share a sentence with CCL3L3 in 1 paper.